KDM4A (lysine demethylase 4A)
Diseases named in the same sentence as KDM4A in open-access papers (continued):
Sharing a sentence is not in itself a finding about the gene and the disease.
colorectal cancer (10 papers, 2017 to 2025). A primary or metastatic malignant neoplasm that affects the colon or rectum. "Using the chemical KDM4 protein inhibitor QC6352 as well as KDM4A silencing by epi-editing, we corroborated the ability of inhibiting KDM4 to reduce cancer cell viability for breast and colorectal cancers." (PMID 40537846, 2025).
gastric cancer (9 papers, 2017 to 2025). A primary or metastatic malignant neoplasm involving the stomach. "Furthermore, KDM4A and KDM4B are often amplified in gastric cancer, neuroblastoma, and ovarian cancer." (PMID 30683841, 2019). "Here, we show that the silencing of KDM4B, but not KDM4A/KDM4C, with specific shRNAs significantly reduced IL-8 production in gastric cancer cells." (PMID 30683841, 2019).
leukemia (9 papers, 2017 to 2026). A malignant (clonal) hematologic disorder, involving hematopoietic stem cells and characterized by the presence of primitive or atypical myeloid or lymphoid cells in the bone marrow and the blood. "KDM4A is found in several subtypes of leukemia and mediates their self-renewal, proliferation, and survival during leukemogenesis." (PMID 37692513, 2023). "According to in vitro and in vivo biological function experiments, KDM4A (JMJD2A) inhibitor SD49-7 suppressed the progression of leukemia stem cells through the activation of the apoptosis signaling pathway." (PMID 36671446, 2022). "To further investigate KDM4A function in human leukemia cells, we used the human myeloid leukemia cell line THP-1 and performed subsequent experiments using the most efficient of three different shRNAs." (PMID 35836814, 2022). "Upregulation of KDM4A in AML cells prompted us to investigate its function in leukemogenesis using an MLL-AF9 leukemia mouse model." (PMID 35836814, 2022). "Loss of KDM4A significantly prolonged overall survival (OS) of mice with only one mouse succumbing to leukemia over the follow-up period by either KDM4A#1 KD or KDM4A#2 KD." (PMID 34083515, 2021). "From this regulatory network, we further extracted a KDM4A-9 gene signature enriched with leukemia stem cell activity; the KDM4A-9 score alone or in combination with the known LSC17 score, effectively stratifies high-risk AML patients." (PMID 34083515, 2021). "In the present study, we found that depletion of KDM4A by either shRNA or its inhibitor SD49-7 could sufficiently impede leukemogenesis, indicating that KDM4A may be a more suitable target in impairing leukemia cells." (PMID 35836814, 2022). "Moreover, the colony formation numbers of leukemia cells, especially the most malignant colony type A 23, were significantly reduced by KDM4A knockdown." (PMID 35836814, 2022). "Furthermore, transplantation of KDM4A-silenced leukemia cells significantly lowered the percentage of leukemia cells in the peripheral blood of recipient mice." (PMID 35836814, 2022). "Other KDM4 family members (i.e., KDM4A, KDM4C, and KDM4D) were found to be expressed at lower and similar levels across the cytogenetic subgroups of AML including the mixed lineage leukemia gene‐associated leukemia (11q23/MLL) etc.." (PMID 34938963, 2021). "Apoptosis results from a global accumulation of H3K9me3 and H3K27me3 at KDM4A genomic loci thereby causing downregulation of a KDM4A-PAF1-mediated oncogenic program, including a 9-gene signature enriched with leukemia stem cell (LSC) activity, which can stratify high-risk patients." (PMID 34083515, 2021). "Also, the GFP+ leukemia cells could hardly be detected in the bone marrow (BM) of the recipients of KDM4A KD cells." (PMID 35836814, 2022). "We found that the mRNA level of KDM4A was slightly decreased by SD49-7 in both THP-1 and MLL-AF9 leukemia cells, whereas it decreased KDM4A and KDM4C protein levels only in THP-1 cells, but not in MLL-AF9 leukemia cells." (PMID 35836814, 2022). "A previous study revealed that combined activity of Kdm4a, Kdm4b, and Kdm4c is required for AML with a rearrangement of the mixed‐lineage leukemia gene (MLL‐AF9‐translocated AML) in vitro and in vivo, using Kdm4a−c triple knockout mice." (PMID 34938963, 2021). "Taken together, compared to SD70, SD49-7 could efficiently inhibit KDM4A and KDM4C, resulting in leukemia suppression." (PMID 35836814, 2022). "Thus, we provided evidence that among the KDM4 family, KDM4A and KDM4C are the most efficient potential targets in leukemia treatment." (PMID 35836814, 2022). "We have shown that the small molecule compound SD49-7, which targets KDM4A and KDM4C, could inhibit leukemia progression." (PMID 35836814, 2022).
leukemia (continued). "Depleting KDM4A and KDM4C by either shRNA or SD49-7 enhanced trimethylation of H3K9 occupying the promoter of MDM2 and activated p21CIP1 by decreasing MDM2 expression, inhibiting the stemness and proliferation, and activating apoptosis of leukemia cells." (PMID 35836814, 2022). "Furthermore, only simultaneous knockout of the demethylases Kdm4a, Kdm4b, and Kdm4c perturbed progression of MLL-AF9 translocated leukemias in mice." (PMID 34944554, 2021). "In this study, we found that KDM4A expression levels were significantly higher in several human leukemia subtypes, and silencing of Kdm4a could sufficiently inhibit the leukemogenic ability in an in vivo MLL-AF9 leukemia model." (PMID 35836814, 2022). "We demonstrated that KDM4A and KDM4C, but not KDM4B, regulated leukemia progression." (PMID 35836814, 2022).
nasopharyngeal carcinoma (9 papers, 2017 to 2025). A carcinoma arising from the nasopharyngeal epithelium. "The increased expression of KDM4A was also observed in nasopharyngeal carcinomas, and it correlated with clinical stage, metastasis, and worse prognosis." (PMID 35326475, 2022). "KDM4A was shown to promote the proliferation, migration, and invasion of nasopharyngeal cancer cells." (PMID 35326475, 2022). "Lysine specific demethylase 4A (KDM4A) is encoded by a cancer-associated gene and is overexpressed in tumors including human nasopharyngeal carcinoma." (PMID 34385569, 2021). "Compelling evidence has indicated the vital role of lysine-specific demethylase 4 A (KDM4A), hypoxia-inducible factor-1α (HIF1α) and the mechanistic target of rapamycin (mTOR) signaling pathway in nasopharyngeal carcinoma (NPC)." (PMID 34385569, 2021).
glioma (8 papers, 2016 to 2025). A benign or malignant brain and spinal cord tumor that arises from glial cells (astrocytes, oligodendrocytes, ependymal cells). "The presence of D-2-HG in IDH1/2 mutated gliomas induced inhibition of KDM4A, which decreases the half-life and protein level of DEPTOR, and further enhances mTORC1/2 kinase activities." (PMID 34571995, 2021). "In IDH1/2 mutated gliomas, the high concentration of D-2-HG could suppress the function of KDM4A, KDM4B, and KDM4C (also known as JmjC-KDM2A, JmjC-KDM2B, and JmjC-KDM2C), and increase histone methylation levels, such as H3K9me3, H3K9me2, H3K36me3, and H3K4me3." (PMID 34571995, 2021). "This newly revealed PTEN-independent mode of mTORC1/2 activation via the mutated IDH/2HG/KDM4A/DEPTOR pathway may provide an additional molecular mechanism to explain the oncogenic activity of IDH1/2 mutations in glioma and other cancers." (PMID 27624942, 2016). "Endogenous KDM4A and DEPTOR are also associated in 293E, HeLa, as well as in glioma-related central nervous system-derived cells, that is, immortalized normal human astrocytes (NHAs)." (PMID 27624942, 2016). "In glioma, KDM4A promotes cell survival by inhibiting autophagy in U87MG and T98G cells." (PMID 37692513, 2023). "Mechanistically, KDM4A interacts with DEPTOR and reduces its ubiquitination, and the stability of DEPTOR negatively modulates the mammalian (mechanistic) target of rapamycin (mTOR) 1/2 and inhibits autophagy and apoptosis in glioma." (PMID 37692513, 2023).
cervical carcinoma (7 papers, 2021 to 2024). A carcinoma arising from either the exocervical squamous epithelium or the endocervical glandular epithelium. "In cervical cancer cells, HIF1α is epigenetically regulated by lysine (K)-specific demethylase 4A (KDM4A), which, in turn, was found to be upregulated under hypoxic conditions." (PMID 38612455, 2024). "In cervical cancer, KDM4A was found to promote proliferation and inhibit apoptosis of cervical cancer cells by reducing the tumor suppressor miR-491-5p." (PMID 37692513, 2023).
colon carcinoma (7 papers, 2014 to 2025). "Knockdown of KDM4A led to reduction of the proliferation in three different colon cancer cell lines (HCT116, DLD-1, and HT-29)." (PMID 29651880, 2018). "The most potent of these analogs, 9bf, displayed the highest KDM4A inhibitory enzymatic activity in vitro (IC50 of 10.1 and 24.37 μM) in colon cancer cells, and the strongest antitumor action in several solid and hematological human cancer cell lines with no toxic effect in normal cells." (PMID 32523934, 2020).
ovarian carcinoma (7 papers, 2020 to 2022). A malignant neoplasm originating from the surface ovarian epithelium. "The expression of lysine-specific demethylase 4A (KDM4A) was shown to be dysregulated in several tumors such as ovarian cancer." (PMID 33568205, 2021). "KDM4A, B, C, and D’s expression is tightly regulated in non-neoplastic tissues but often deregulated in several neoplasias such as prostate, liver, bladder, colorectal, squamous cell carcinomas, acute myeloid leukemia, breast, lung and ovarian cancer." (PMID 35480330, 2022).
ischemic stroke (5 papers, 2017 to 2025). A stroke disorder caused by obstruction of blood flow to the brain, due to thrombotic (local blood clot formation) or embolic (due to a blood clot or other material traveling from another site) event. "KDM4A reduces functional recovery in ischemic stroke by activating NF-κB downstream genes and subsequent neuroinflammation." (PMID 37692513, 2023). "In this context, they also suggest that KDM4A might represent a novel target for epigenetic therapy in the prevention and treatment of atherosclerotic diseases, particularly their fatal complications such as heart attack and ischemic stroke." (PMID 29383092, 2017). "Moreover, KDM4A can increase MDM2 expression and reduce CTRP3 expression in microglia, thereby promoting polarization and exacerbating brain injury after ischemic stroke in mice." (PMID 40600192, 2025).
non-small cell lung carcinoma (5 papers, 2015 to 2024). A group of at least three distinct histological types of lung cancer, including non-small cell squamous cell carcinoma, adenocarcinoma, and large cell carcinoma. "In a study of human non-small cell lung cancer (NSCLC), DLX5 was determined to be activated by KDM4A-mediated demethylation, and in turn, DLX5 induced the expression of MYC and β-catenin, thereby, promoting proliferation and metastasis." (PMID 34203994, 2021). "The tri-methyl selective KDM4A/JMJD2A demethylase is an AR coregulator expressed in PCa and is a determinant of mTOR inhibitor sensitivity in non-small cell lung cancer patients." (PMID 26461474, 2015).
squamous cell carcinoma (5 papers, 2018 to 2025). A carcinoma arising from squamous epithelial cells. "KDM4A is a histone demethylase that targets histone H3 lysine 9 trimethylation (H3K9me3) and is associated with the development of squamous cell carcinoma growth and metastasis." (PMID 34830754, 2021). "The level of KDM4A protein was significantly increased in metastatic lymph nodes in comparison to primary human squamous cell carcinomas, which links KDM4A with promoting metastasis in this type of cancer." (PMID 35326475, 2022). "In the STING modification of epigenetic changes in squamous cell carcinoma, KDM4A inhibition activates immune responses to squamous cell carcinoma and enhances the therapeutic potential of anti-PD-1 antibody treatment for squamous cell carcinoma." (PMID 34830754, 2021). "More KDM genes, including KDM4B, KDM2B, and KDM4A for adenocarcinomas and KDM2B, KDM4C, and KDM4B for squamous cell carcinomas, appear to be associated with patients’ survival." (PMID 29619118, 2018). "Squamous cell carcinoma (SCC) metastasis, invasive growth, and the synthesis of AP-1 transcription factors were all aided by a unique LSD called KDM4A (lysine-specific demethylase 4A)." (PMID 39991574, 2025).
acute myeloid leukemia (4 papers, 2021 to 2023). Acute myeloid leukemia (AML) is a group of neoplasms arising from precursor cells committed to the myeloid cell-line differentiation. "Recently, an increasing number of studies have shown that pharmacological inhibition of KDM4A significantly attenuates tumor progression in vitro and in vivo in a range of solid tumors and acute myeloid leukemia." (PMID 37692513, 2023). "For the therapy of Acute Myeloid Leukemia, since KDM4A, D and E are involved, the CNP0131606 is promising given the fact that it could target those three enzymes." (PMID 35480330, 2022).
hepatocellular carcinoma (4 papers, 2020 to 2025). A malignant tumor that arises from hepatocytes. "Only in the hepatocellular carcinoma cells (HepG2), the co-transfection of sgRNA-KDM4A with dCas9-VP64 increased the KDM4A gene expression by 2.2-fold (p = 0.025) compared to cells co-transfected with dCas9-NED." (PMID 40537846, 2025). "Conversely, another group has reported upregulation of KDM4A in hepatocellular carcinoma and demonstrated a functional oncogenic role for KDM4A, as its overexpression promoted cell proliferation." (PMID 40537846, 2025). "In summary, RFX5 transcriptionally activates KDM4A expression, which drives hepatocellular carcinoma progression by inhibiting apoptosis, accelerating cell cycle transition and subsequently promoting HCC development." (PMID 32883983, 2020). "Upon validating the downregulation of KDM4A in HEK293T cells through epi-editing, we demonstrated its repression in colon, breast and hepatocellular carcinomas which was effective in preventing (breast, MCF7) or inhibiting (colon, HCT116) cancer cell growth." (PMID 40537846, 2025). "Our studies, however, do not demonstrate any involvement of KDM4A in HCT116 hepatocellular carcinoma proliferation, neither through epi-editing nor by siRNA downregulation." (PMID 40537846, 2025). "Indeed, we confirmed overexpression of KDM4A in theses tumor types, while no significant overexpression of KDM4A was observed in patient hepatocellular carcinoma tissue compared to normal tissue in our TCGA dataset analyses." (PMID 40537846, 2025).
liver cancer (4 papers, 2017 to 2023). An epithelial or non-epithelial malignant neoplasm that arises from the liver. "Previous study has reported that KDM4A could promote malignant proliferation of human liver cancer cell line Hep3B, which was consistent with our findings." (PMID 32883983, 2020).
pancreatic cancer (4 papers, 2020 to 2025). "b mRNA expressions of KDM4A in the pancreatic cancer-cell lines PANC-1 and BxPC-3 with treatment of fisetin were detected by qRT-PCR." (PMID 33093461, 2020). "To further determine the role of KDM4A in pancreatic cancer cells, we depleted KDM4A with CRISPR/Cas9 in PANC-1 cells." (PMID 33093461, 2020). "SIRT2 acts as a tumor suppressor and an oncogene; it interacts with β-catenin and lysine-specific demethylase 4A (KDM4A) to inhibit cell growth, and is involved in survival and cell proliferation in pancreatic cancer, hepatocarcinoma, and neuroblastoma." (PMID 35054489, 2022).
atherosclerosis (3 papers, 2017 to 2023). A disease characterized by the build-up of fatty material and calcium deposition in the arterial wall resulting in partial or complete occlusion of the arterial lumen. "Other than that, KDM3A has been identified as important regulator of neointima formation in experimental atherosclerosis whilst KDM4A mediates oxidized LDL-induced pro-inflammatory Mac polarization." (PMID 36552592, 2022). "The proliferation and migration of vascular smooth muscle cells (VSMCs) are two crucial cell events in atherosclerosis, and KDM4A was found to promote these two processes by inhibiting cyclin D1 expression and increasing p21 expression in a demethylase-dependent manner." (PMID 37692513, 2023). "Of note, targeting KDM4A not only prevented oxLDL-induced M1 polarization of macrophages, but also redirected them towards anti-inflammatory M2 phenotype that is known to promote inflammation resolution in atherosclerosis." (PMID 29383092, 2017). "A possibility thus arises that KDM4A might participate in uncontrolled inflammation, which is required for initiation and progression of atherosclerosis, by governing oxLDL-induced pro-inflammatory M1 polarization of macrophages." (PMID 29383092, 2017). "As another member of the Jumonji family, KDM4A has been widely studied in cancer, while not yet in either macrophages or inflammatory diseases including atherosclerosis." (PMID 29383092, 2017). "Although KDM4A is one of the most studied KDMs in cancer, neither its role in regulation of macrophage function and inflammation nor its relationship with oxLDL and atherosclerosis has been explored before." (PMID 29383092, 2017). "Interestingly, oxLDL-mediated up-regulation of KDM4A was independent of activation of the NF-κB and HIF signaling pathways that are known to be involved in macrophage activation under diverse inflammatory conditions including atherosclerosis." (PMID 29383092, 2017).
head and neck squamous cell carcinoma (3 papers, 2017 to 2024). A squamous cell carcinoma that arises from any of the following anatomic sites: lip and oral cavity, nasal cavity, paranasal sinuses, pharynx, larynx, and salivary glands. "KDM4A, for instance, is frequently overexpressed in cancers, including head and neck squamous cell carcinoma (HNSCC)." (PMID 39519018, 2024). "In head and neck squamous cell carcinoma (HNSCC), KDM4A is overexpressed in HNSCC and lymph node metastasis tissue and promotes the invasion and metastasis of HNSCC." (PMID 37692513, 2023).
lung adenocarcinoma (3 papers, 2022 to 2024). A carcinoma that arises from the lung and is characterized by the presence of malignant glandular epithelial cells. "In KM-plotter analysis of patients with lung adenocarcinoma, high expression of KDM4A was associated with shorter overall survival." (PMID 39085849, 2024).
mood disorder (3 papers, 2020 to 2023). A cognitive disorder a disturbance in which the person's mood is hypothesized to be the main underlying feature. "KDM4A promotes glial activation in neonatal mice and causes adult mood disorders through epigenetic regulation." (PMID 37692513, 2023).
oral squamous cell carcinoma (3 papers, 2017 to 2023). "The purpose of this study was to examine KDM4A as an independent prognostic marker in oral squamous cell carcinoma, using multicenter tissue microarrays." (PMID 29113308, 2017).